MMP7 (matrix metallopeptidase 7)
Diseases named in the same sentence as MMP7 in open-access papers (continued):
Sharing a sentence is not in itself a finding about the gene and the disease.
prostate adenocarcinoma (4 papers, 2018 to 2024). "Currently, IL-17 has been shown to promote prostate adenocarcinoma while increasing matrix metalloproteinase 7 (MMP7) expression in mouse prostate." (PMID 36292723, 2022). "All testicular germ cell tumors (TGCT) with a ~1.5% frequency, prostate adenocarcinoma (PRAD) with a ~1% frequency, and KIRP (< 1% frequency) cases with genetic alterations were found to hold the copy number deletion of MMP7 as their alteration type." (PMID 35785154, 2022).
urothelial bladder cancer (4 papers, 2014 to 2023). "Serum MMP-7 is a validated prognostic marker in urothelial bladder cancer, a tumour entity with large clinical, histological, and molecular similarity to UTUC." (PMID 35327500, 2022). "Plasma from muscle-invasive, urothelial bladder cancer patients displayed higher levels of MMP7 (p = 0.028) and CCL23 (p = 0.03) compared to NMIBC patients, whereas urine displayed higher levels of CD27 (p = 0.044) and CD40 (p = 0.04) in the NMIBC group by two-sided Wilcoxon rank-sum tests." (PMID 37391708, 2023).
acute lung injury (3 papers, 2021 to 2025). A condition of lung damage that is characterized by bilateral pulmonary infiltrates (pulmonary edema) rich in neutrophils, and in the absence of clinical heart failure. "Although its role in ARDS is not fully understood, MMP7 regulates inflammation and mortality in cecal ligation and puncture, intraperitoneal lipopolysaccharide (LPS), and intratracheal bleomycin-induced models of systemic inflammation, lung inflammation, and acute lung injury (ALI)." (PMID 40341670, 2025). "Moreover, MMP-7 has been reported to direct and confine neutrophil influx to sites of injury by mediating shedding of syndecan-1 complexes from the mucosal surface in acute lung injury." (PMID 34130757, 2021). "Matrix metalloproteinase 7 (MMP7) can regulate leukocyte recruitment and the production of pro-inflammatory cytokines, but whether it plays a role in acute lung injury (ALI) is an unanswered question." (PMID 40341670, 2025).
acute respiratory distress syndrome (3 papers, 2020 to 2024). Progressive and life-threatening pulmonary distress in the absence of an underlying pulmonary condition, usually following major trauma or surgery. "Moreover, MMPs are involved in tissue repair, as MMP7 and MMP9 have been reported to participate in epithelial tissue repair after damage caused by acute respiratory distress syndrome (ARDS)." (PMID 33271804, 2020). "A recent study showed one week after admission, obese-diabetic patients with acute respiratory distress syndrome (ARDS) demonstrated notably elevated levels of MMP7 and MMP9 in their serum compared to non-ARDS patients, indicating increased activation of macrophages." (PMID 38803919, 2024).
ameloblastoma (3 papers, 2021 to 2024). The most common odontogenic tumor, arising from the epithelial component of the embryonic tooth and usually affecting the molar-ramus region of the mandible or maxilla. "In this study, we used immunohistochemistry to investigate the MMP‐7, ‐8, ‐9, beta‐catenin, and E‐cadherin immunoexpression in primary and recurrent ameloblastoma tissue samples from 34 patients." (PMID 32985799, 2021). "We investigated the involvement of MMP‐7, ‐8, ‐9, E‐cadherin, and beta‐catenin in ameloblastoma and the surrounding extracellular matrix." (PMID 32985799, 2021). "Several studies also demonstrated that MMPs like MMP-1, MMP-2, MMP-7, MMP-9 and MMP-14 are involved in ECM degradation in the invasion of ameloblastoma [16,21,22,]." (PMID 35243014, 2022). "In this study, we explored the expression of MMP‐7, ‐8, ‐9, beta‐catenin, E‐cadherin in the ECM and ameloblastoma tumor cells and evaluated the role of those markers combined with clinical factors in predicting recurrence of ameloblastoma." (PMID 32985799, 2021). "MMP‐7 was expressed only in apoptotic or mitotic cells in the basal layer of ameloblastoma tumor tissue which otherwise was negative." (PMID 32985799, 2021). "In our material neither nuclear beta‐catenin nor MMP‐7 expression were detected in ameloblastoma cells except for some single positive apoptotic or mitotic cells." (PMID 32985799, 2021). "This raises the question, could the absence of osteoclast derived MMP‐7 in ameloblastomas provide protection against more aggressive behavior?" (PMID 32985799, 2021).
Barrett esophagus (3 papers, 2010 to 2023). Esophageal lesion lined with columnar metaplastic epithelium which is flat or villiform. "Immunohistochemistry revealed that MMP‐7 was weakly expressed in normal squamous epithelium adjacent to EAC but was abundant in epithelial cells in both preneoplastic lesions of Barrett's esophagus and EAC particularly at the invasive front." (PMID 29845775, 2018). "We have now examined how MMP‐7 expression changes in the progression to esophageal adenocarcinoma (EAC), and have studied mechanisms regulating its expression and its functional significance." (PMID 29845775, 2018). "To examine in more detail the expression of MMP‐7 in myofibroblasts we screened three different esophageal adenocarcinoma‐derived CAMs." (PMID 29845775, 2018). "To establish whether PEA3 subfamily members might also play a role in controlling MMP expression in human cancers, we determined the levels of MMP-1 and MMP-7 mRNA expression in tissue samples from patients with oesophageal adenocarcinomas." (PMID 21143918, 2010). "Unlike many MMPs, MMP7 is typically expressed in epithelial cells, and MMP7 expression increases at the invasive front in esophageal adenocarcinoma which may be partly attributable to the activation of PI3K." (PMID 36677584, 2023).
cardiac hypertrophy (3 papers, 2015 to 2023). "In contrast to our observations of downregulation of MMPs, in animal models with induction of cardiac hypertrophy, MMPs are often found to be upregulated, i.e., under AngII infusion, induction of MMP-7 was shown; under norepinephrine infusion or pressure overload, MMP-2 was induced." (PMID 33400052, 2021). "Contrarily, AT-001 treatment did not influence the myocardial expression of MMP9 and MMP7, both of which are potent regulators of cardiac fibrosis and hypertrophy." (PMID 36978133, 2023).
cervical dysplasia (3 papers, 2012 to 2025). "In the present study we found increasing staining for MMP-16 along with the development of cervical dysplasia, in agreement with a number of previous studies, whereas MMP-7 expression remained virtually similar." (PMID 22863036, 2012).
colon adenoma (3 papers, 2015 to 2023). An adenoma that arises from the colon. "Consistent with this, the Paneth cell marker MMP7, which was among the few Wnt target genes deregulated in the normal epithelium of Bcat mice, was already significantly upregulated in benign human colonic adenoma." (PMID 26398937, 2015). "Interestingly, only Mmp7 and Mmp13 displayed a significantly higher level of activation in colon adenomas compared with both the adjacent tissue (13.8- and 13.4-fold increase, respectively) and colon tissue with acute colitis (186.4- and 19.6-fold increase, respectively)." (PMID 36901742, 2023).
cyst (3 papers, 2022 to 2024). A sac-like closed membranous structure that may be empty or contain fluid or amorphous material. "In the diseased kidney, MMP-7 is detected in tubular and cyst-lining epithelium, and can cause proteinuria by cleaving slit diaphragm proteins." (PMID 35136035, 2022). "After adjusting for age, serum MMP-7 demonstrated a significant positive correlation with both the mean relative cyst diameter (1.85 ± 1.27, r = 0.404, p < 0.001) and mean relative cyst length (3.28 ± 1.58, r = 0.402, p < 0.001) in all CDC patients." (PMID 38914992, 2024). "MMP‐7 median serum levels were significantly elevated in the PDAC group compared with the cyst group (7.3 ng/mL [IQR 4.8–14.5] vs. 3.7 ng/mL [IQR 2.9–5.0], respectively; p < 0.001)." (PMID 39263943, 2024). "Patients with elevated serum MMP-7 were more likely to experience severe obstruction of the distal end of the common bile duct, as evidenced by abnormal laboratory tests (higher levels of GGT, TB, and DB), larger cyst sizes, and higher incidence of perforation." (PMID 38914992, 2024).
depression (3 papers, 2017 to 2024). "Recent work has also shown that MMP-7 is increased with major depression, a condition that is increasingly associated with microglial activation." (PMID 28302163, 2017).
dysplasia (3 papers, 2023 to 2025). A usually neoplastic transformation of the cell, associated with altered architectural tissue patterns. "MMP7 correlates with the grade of ulcerative colitis-associated dysplasia or carcinoma." (PMID 39419989, 2024). "In our study we tried to assess the potential of MMP-3, MMP-7, MMP-10, and MMP-26, which showed significant differences in concentrations between the groups of healthy women, dysplasia patients, and cancer patients, and also demonstrated the ability to distinguish benign from malignant lesions." (PMID 41462922, 2025). "Compared to ulcerative colitis without dysplasia, MMP-7 expression is increased at the crypt bases of CAC tissue and its expression is more widespread in high-grade compared to low-grade dysplasia." (PMID 38288108, 2023).
encephalitis (3 papers, 2009 to 2025). An acute inflammatory process affecting the brain parenchyma. "In JE in mice, MMP9 is vividly upregulated intrathecally simultaneously with the development of the histopathological features of encephalitis, accompanied by MMP2 and MMP7." (PMID 40003967, 2025). "MMP7 was little studied in viral encephalitis before and to our knowledge has never been described as a pathogenetic factor in TBE before." (PMID 40003967, 2025). "MMP7 has not been commonly studied in the context of viral encephalitis and its relevance is unknown." (PMID 30442185, 2018). "Perivascular cuffing, a classic feature of encephalitis, was not seen in the brains of MOG-primed mmp7-/- mice." (PMID 19267908, 2009).
experimental autoimmune encephalomyelitis (3 papers, 2009 to 2018). An autoimmune demyelinating disease of the central nervous system that is produced experimentally in animals by the injection of homogenized brain or spinal cord in Freund's adjuvant. "However, MMP7 is important for leukocyte infiltration during experimental autoimmune encephalomyelitis and is found in the CSF during AIDS dementia." (PMID 30442185, 2018). "Rather, in a model of experimental autoimmune encephalomyelitis (EAE) induced by myelin oligodendrocyte glycoprotein (MOG) exposure, splenocytes and lymphocytes from Mmp7-/- mice were able to respond to MOG and induce EAE in wild type mice." (PMID 26933888, 2016).
idiopathic interstitial pneumonia (3 papers, 2013 to 2025). A class of diffuse lung diseases that typically affect the pulmonary interstitium, although some also have a component affecting the airways (for instance, Cryptogenic organizing pneumonitis). "Plasma SPP1 levels—either alone or in combination with surfactant protein-D (SP-D) and MMP-7—have been shown to differentiate IPF from other idiopathic interstitial pneumonias (IIPs)." (PMID 40559389, 2025).
infertile (3 papers, 2009 to 2024). "Furthermore, new data on transcriptomic profiling suggest a different expression of MMP7 between fertile and infertile females." (PMID 28293067, 2017). "In a previous study, MMP7 has been shown to be expressed during the receptive phase localized to endometrial glandular and luminal epithelium with low transcript levels found in infertile patients." (PMID 20040080, 2009). "Women with infertility or recurrent miscarriages have lower levels of endometrial VEGF expression and peripheral blood levels of MMP-7 and VEGF, suggesting that angiogenesis plays a role in implantation and placenta development." (PMID 38397233, 2024).
Insulin resistance (3 papers, 2016 to 2024). Increased resistance towards insulin, that is, diminished effectiveness of insulin in reducing blood glucose levels. "Additionally, we are contrasting the homeostatic model assessment for insulin resistance (HOMA-IR) values with urine MMP-7 values to provide a predictive value for glycemic excursion and insulin sensitivity." (PMID 39246865, 2024).
ischemic stroke (3 papers, 2019 to 2020). A stroke disorder caused by obstruction of blood flow to the brain, due to thrombotic (local blood clot formation) or embolic (due to a blood clot or other material traveling from another site) event. "Similar to MMP-7 in the present study, elevated lipoprotein (a) in patients with acute first ischaemic stroke has been associated with a higher risk of combined recurrent cardiovascular events." (PMID 32101136, 2020). "MMP7 rs10502001 was associated with ischemic stroke in a dominant model." (PMID 31752174, 2019). "They found that MMP-7 may be a potential risk marker for ischemic stroke." (PMID 31752174, 2019). "In summary, we found that a wGRS that includes variants of MMP-7, MMP-8 and MMP-26 was associated with increased risk of ischemic stroke." (PMID 31752174, 2019). "In our study, the wGRS summarizing the influence of MMP-7, MMP-8 and MMP-26 was associated with ischemic stroke." (PMID 31752174, 2019). "Although the results from our study need to be replicated in other studies, our data suggest that a cumulative effect of genetic variants from MMP-7, MMP-8 and MMP-26 on the risk of ischemic stroke." (PMID 31752174, 2019). "There was a significant interaction between high genetic and high modifiable CVD risk, indicating that the combined genetic risks from MMP-7, MMP-8 and MMP-26 may modify the association of high modifiable CVD risk with ischemic stroke." (PMID 31752174, 2019). "Additionally, activated matrix metalloproteinases (MMPs), such as MMP-2, MMP-3, MMP-7, and MMP-9, induce BBB disruption in experimental ischemic stroke and severe inflammatory response following septic shock." (PMID 31547411, 2019).
leukemia (3 papers, 2016 to 2025). A malignant (clonal) hematologic disorder, involving hematopoietic stem cells and characterized by the presence of primitive or atypical myeloid or lymphoid cells in the bone marrow and the blood. "Other studies have focused on the connection between MMP-2 and MMP-7 genotypes and the risk of childhood leukemia." (PMID 39996769, 2025). "Most recent studies have focused on the connection between MMP-2 and MMP-7 genotypes and the risk of childhood leukemia." (PMID 32751899, 2020). "Researchers from Taiwan concluded that although MMP-2 promoter genotypes play a minor role in the assessment of the risk of developing leukemia, the MMP-7 A-181G genotype may serve as a predictive biomarker for childhood ALL." (PMID 32751899, 2020). "This study emphasized that MMP-7 may play an important role in leukemia cell invasion." (PMID 32751899, 2020). "Other MMPs that we also showed to be regulated by eIF2α-P, MMP-7 and MMP-12, were found to potentiate invasion of leukemia cells." (PMID 27802179, 2016).
liver disease (3 papers, 2023 to 2026). "However, while MMP-7 evaluations may be possible in paediatric liver disease centres, for most clinicians, the MMP-7 level is not a primary evaluation parameter, since many clinicians may be unaware of its significance and most hospitals may not be equipped to perform MMP-7 assays." (PMID 37907911, 2023).
mesenchymal tumors (3 papers, 2004 to 2025). "MMP-7 is produced by stromal cells and by tumor cells and is overexpressed in a variety of epithelial and mesenchymal tumors." (PMID 25984271, 2014). "MMP-7 is overexpressed in a variety of epithelial and mesenchymal tumors, such as esophageal, colon, liver, renal and pancreatic cancer." (PMID 25984271, 2014). "What is significant, expression of MMP-7 is enhanced in various epithelial and mesenchymal tumors." (PMID 40427193, 2025). "Therefore, the fact that an upregulation of MMP7 was found in desmoids suggests that it is not only a target of β-catenin in epithelial tumours but probably also in mesenchymal tumours." (PMID 15054469, 2004).
myeloma (3 papers, 2017 to 2023). "The current study clearly demonstrates that inhibition of MMP-7 is an inappropriate approach for the treatment of myeloma and its associated bone disease." (PMID 28241871, 2017). "An increase in tumor burden and osteolytic bone disease was observed in myeloma-bearing MMP-7 deficient mice, as compared to wild-type controls." (PMID 28241871, 2017). "MMP-7 has a number of reported substrates, including some associated with myeloma cell apoptosis such as FASL." (PMID 28241871, 2017). "The significant increase in both tumor burden and the associated osteolytic bone disease in MMP-7−/− mice suggest that host-derived MMP-7 plays a specific tumor-suppressive role in myeloma." (PMID 28241871, 2017). "Our studies have collectively identified an unexpected role for MMP-7 in myeloma pathogenesis, whereby a loss of MMP-7 promotes tumor growth and myeloma bone disease." (PMID 28241871, 2017). "Analysis of patients with multiple myeloma revealed a decrease in systemic MMP-7 activity in multiple myeloma in vivo." (PMID 28241871, 2017). "In the present study, we identified an unexpected tumor-suppressive role for MMP-7 in myeloma pathogenesis." (PMID 28241871, 2017). "Our studies have identified an unexpected tumour-suppressive role for host-derived MMP-7 in myeloma bone disease in vivo, and highlight the importance of elucidating the effect of individual MMPs in a disease-specific context." (PMID 28241871, 2017). "Subsequent histological assessment of the bone marrow demonstrated that the proliferative rate of myeloma cells within the MMP-7−/− environment was greater than that in WT animals." (PMID 28241871, 2017). "A significant decrease in myeloma cell apoptosis was also observed in myeloma-bearing MMP-7−/−mice as compared with WT mice." (PMID 28241871, 2017). "To determine the role of host-derived MMP-7 in myeloma pathogenesis, we used immunocompromized (RAG-2−/−) mice that were wild type or null for MMP-7 and can be successfully engrafted with the 5T myeloma model." (PMID 28241871, 2017). "These in vivo murine myeloma studies are supported by clinical evidence demonstrating a significant reduction in MMP-7 activity in patients with multiple myeloma." (PMID 28241871, 2017). "In contrast and underscoring the complexity of MMP biology, here we identified a tumor-suppressive role for host MMP-7 in the progression of multiple myeloma in vivo." (PMID 28241871, 2017). "A significant increase in tumor burden in myeloma-bearing MMP-7−/− mice was demonstrated by an increase in myeloma-specific IgG2bκ serum concentrations and GFP-positive myeloma cells in the bone marrow and spleen, as compared to myeloma-bearing WT mice." (PMID 28241871, 2017). "Treatment of murine and human myeloma cells with increasing concentrations of recombinant MMP-7 in serum-free media had a limited effect to reduce cell viability, that was not dose-dependent." (PMID 28241871, 2017). "This resulted in an increase in myeloma cell viability that was prevented by overexpression of MMP-7 in preosteoblasts." (PMID 28241871, 2017). "Littermate wild-type (WT, Rag2−/−;MMP-7+/+) and MMP-7 homozygous deficient (MMP-7−/−, Rag2−/−; MMP-7−/−) mice were inoculated with 5TGM1 myeloma cells." (PMID 28241871, 2017). "As shown here, MMP-7 activity was reduced in the serum of both myeloma-bearing mice and in patients with multiple myeloma." (PMID 28241871, 2017). "In the present study, we have identified host-derived MMP-7 as having a tumor-suppressive role in myeloma." (PMID 28241871, 2017). "We observed that systemic MMP-7 activity was reduced in tumor-bearing mice and, in patients with multiple myeloma this reduced activity was concomitant with increased levels of the endogenous MMP inhibitor, tissue inhibitor of metalloproteinases-1 (TIMP-1)." (PMID 28241871, 2017).